STAT3 (signal transducer and activator of transcription 3)
Diseases named in the same sentence as STAT3 in open-access papers (continued):
Sharing a sentence is not in itself a finding about the gene and the disease.
Fulminant hepatitis (1 paper, 2024). Acute hepatitis complicated by acute liver failure with hepatic encephalopathy occurring less than 8 weeks after the onset of jaundice. "Previous studies have reported implications of MDM2 and COP1 that targeted STAT3 for degradation in tumorigenesis, and involvement of MDM2 in RACK1-abrogated HDAC1 degradation during the pathogenesis of fulminant hepatitis." (PMID 39024388, 2024).
gastric disease (1 paper, 2015). "Although an acute Th2 response may be beneficial by preventing unchecked Th1/Th17 inflammation, we have shown that chronic Th2 activation produces M2 macrophage polarization and increased STAT3 activation, both of which cause gastropathy, being particularly marked in the gastric cardia." (PMID 28210674, 2015). "This suggests that IL33-induced gastric pathology is dependent on infiltrating immune cells, which in turn induce STAT3, leading to gastropathy." (PMID 28210674, 2015).
gastroesophageal junction adenocarcinoma (1 paper, 2018). A carcinoma that arises from glandular epithelial cells of the esophagogastric junction. "Boston Biomedical Inc. conducted a phase 3 clinical trial of the STAT3 inhibitor BBI608 in patients with advanced, previously treated gastric, and gastroesophageal junction adenocarcinoma." (PMID 29849601, 2018).
gestational diabetes (1 paper, 2023). Carbohydrate intolerance first diagnosed during pregnancy. "Additionally, through testing the serum, placenta, and umbilical cord blood of GDM patients, researchers have found that elevated expression of STAT3 is involved in regulating metabolic pathways and the occurrence of gestational diabetes." (PMID 38235138, 2023).
Gliosis (1 paper, 2023). Gliosis is the focal proliferation of glial cells in the central nervous system. "Interestingly, we have found no GFAP and STAT3 positivity in the tumoral areas, though GFAP+ and GFAP+/STAT3+ were highly expressed in areas corresponding to RN and gliosis." (PMID 37762522, 2023).
heart injuries (1 paper, 2021). "Furthermore, although STAT-3 has been shown to be effective in mediating Ang-II–induced heart injuries and the inhibition of STAT-3 reverses these injuries, gene knockout mice demonstrated STAT-3 deficiency as aggravating to Ang-II–induced heart injuries." (PMID 34490381, 2021).
helminth infections (1 paper, 2017). "In the process of M2 polarization and helminth infection, the immune response of the host to helminth infections is strikingly dominated by a Th2 response with a significant production of IL-4, IL-10, IL-13, and the STAT3/STAT6 signaling pathways have been detected." (PMID 28983296, 2017).
hemophagocytic syndrome (1 paper, 2022). "Namely, the definition of the HIES of genetic origins other than mutations in STAT3 or differences between the familial or acquired forms of hemophagocytic syndromes required modifications of the original definitions." (PMID 34797428, 2022).
Henoch-Schönlein purpura (1 paper, 2021). "Characterized in a Henoch-Schönlein purpura rat model, SH2-domain-containing tyrosine phosphatase 2 (SHP2) is another potential modulator of macrophage polarization due to its inhibitory effect on the M2 polarization-promoting STAT3 signaling pathway while also actively inducing M1 polarization." (PMID 35008531, 2021).
hepatopulmonary syndrome (1 paper, 2020). Hepatopulmonary syndrome (HPS) is a lung disease characterized by widening of arteries and veins (dilatation) in the lungs in people who have chronic liver disease. "IL-6-stimulated activation of JAK/STAT3 signaling promoted cell proliferation in pulmonary microvascular endothelial cells (PMVECs) with hepatopulmonary syndrome." (PMID 32635504, 2020). "In a rat model of the hepatopulmonary syndrome, miR-101 inhibited the JAK2/STAT3 signaling pathway by targeting JAK2, thereby inhibiting the proliferation of PMVECs." (PMID 32635504, 2020).
Hereditary breast cancer (1 paper, 2019). Breast carcinoma that has developed in relatives of patients with history of breast carcinoma.
hereditary spherocytosis (1 paper, 2021). Hereditary spherocytosis is a congenital hemolytic anemia with a wide clinical spectrum (from symptom-free carriers to severe hemolysis) characterized by anemia, variable jaundice, splenomegaly and cholelithiasis. "Our case shows an atypical presentation of STAT3 GOF associated with hereditary spherocytosis, and how achievement of a good long-term outcome depends on a strict clinical and laboratory monitoring, as well as on prompt therapeutic intervention." (PMID 33519826, 2021).
HIES syndrome (1 paper, 2020). "This conclusion is made based on greatly reduced reprograming efficiency of primary skin fibroblasts derived from patients with AD-HIES syndrome, carrying dominant negative mutations in STAT3." (PMID 32580970, 2020).
histiocytic lymphoma (1 paper, 2020). "Stimulation of U-937 cells, a standard human monocytic cell line originating from a histiocytic lymphoma, with hIL-6 induced robust STAT3 phosphorylation." (PMID 32365119, 2020).
Hyperammonemia (1 paper, 2024). An increased concentration of ammonia in the blood. "Hyperammonemia enhances the activation of the IL-17 receptor in microglia, leading to increased phosphorylation and activation of STAT3, which increases transcription of IL-17 in microglia, in agreement with previous reports." (PMID 38671534, 2024). "We therefore analyzed the effects of hyperammonemia and of anti-IL-17 on phospho-STAT3 in microglia." (PMID 38671534, 2024). "We show here that IL-17 levels are also increased in cerebellum of rats with hyperammonemia and MHE, leading to increased activation of IL-17 receptor in microglia, which triggers activation of STAT3 and NF-kB, leading to increased levels of IL-17 and TNFα, respectively." (PMID 38671534, 2024). "IL-17 levels and membrane expression of the IL-17 receptor are increased in cerebellum of rats with hyperammonemia and MHE, leading to increased activation of IL-17 receptor in microglia, which triggers activation of STAT3 and NF-kB, increasing IL-17 and TNFα levels, respectively." (PMID 38671534, 2024).
hypereosinophilic syndrome (1 paper, 2016). Hypereosinophilic syndrome (HES) constitutes a rare and heterogeneous group of disorders, defined as persistent and marked blood eosinophilia and/or tissue eosinophilia associated with a wide range of clinical manifestations reflecting eosinophil-induced tissue/organ damage. "A gain of function of STAT3 (p.Y640F) has recently been identified in lymphocytic variant of hypereosinophilic syndrome." (PMID 27222657, 2016).
hyperferritinemia (1 paper, 2025). "In hepatocytes, on the other hand, the presence of IL6 signaling in SUDV-infected cells was predicted to induce hyperferritinemia, the suppression of STAT3, C-reactive protein (CRP), fibrinogen expression and the downregulation of acute phase response." (PMID 41181097, 2025).
hypertensive heart disease (1 paper, 2022). Abnormal enlargement of the heart resulting from long-standing hypertension. "Regarding natural compounds, for instance, celastrol alleviated hypertensive heart disease and cancer metastasis through inhibiting STAT3 and STAT6 signaling, respectively." (PMID 36324680, 2022). "Correspondingly, about nine natural compounds and phytochemicals influence STAT3 signaling for hypertensive heart disease and IBD." (PMID 36324680, 2022).
Hypervolemia (1 paper, 2024). An increase in the amount of intravascular fluid, particularly in the volume of the circulating blood. "Thus, it is quite possible that an insufficient phosphorylation state of STAT3 impairs the quality of the anti-inflammatory response, i.e., the immune response in hypervolemia." (PMID 38612530, 2024).
ileocolitis (1 paper, 2013). Ileocolitis or ileal Crohn's is the most common type of Crohn's disease. "It was recently reported that DC-specific knockout of STAT3 (in Stat3flox/flox × CD11cCre mice), which affects both mDCs and pDCs, leads to a lifelong ileocolitis resembling CD, identifying the deficient STAT3 activity in DCs as an important factor in the development of mucosal inflammation." (PMID 23950992, 2013).
immunoglobulin deficiency (1 paper, 2025). "Patients with STAT3 GOF mutations predominantly presented with lymphoproliferation, characterized by elevated frequencies of double-negative (CD4− CD8−) T cells, autoimmune hematopenia, and hypogammaglobulinemia." (PMID 40703313, 2025).
immunotoxicity (1 paper, 2022). "Aflatoxin B1 can induce immunotoxicity in 3D4/21 cells via the DNA methyltransferase-mediated JAK2/STAT3 pathway." (PMID 36552567, 2022).
infectious mononucleosis (1 paper, 2019). A condition characterized by an increase in mononuclear white blood cells and swollen lymph nodes, which is usually caused by infection with the Epstein-Barr virus. "However, we have also shown that to avoid intra-S phase arrest, EBV disables ATR-mediated phosphorylation of Chk1 through the activities of STAT3 and caspase 7 in cultured EBV-infected cells and in proliferating cells in the blood of patients with infectious mononucleosis." (PMID 31841561, 2019).
infertility disorder (1 paper, 2022). Inability to conceive for at least one year after trying and having unprotected sex. "This study provides evidence that an increase in CatSper, StAR, 3β-HSD, and CYP20A1 and downregulation of STAT3, COX-2, and associated signaling pathways can provide an effective strategy to prevent CDDP-induced reproductive toxicity and infertility disorders." (PMID 36290786, 2022).
interstitial cystitis (1 paper, 2024). A rare chronic debilitating urogenital disease characterized by urinary frequency, urgency, and pelvic pain. "Seven hub genes (SPTBN1, PSME4, CHAC2, ERLEC1, ASB3, STAT5A, and STAT3) were identified as differentially expressed between interstitial cystitis patients and healthy individuals, representing potential therapeutic targets." (PMID 39399486, 2024).
Intracranial aneurysms (1 paper, 2023). "Intracranial aneurysms have been reported in patients with both STAT3 loss-of-function (LOF) and STAT1 GOF." (PMID 36884218, 2023).
large cell medulloblastoma (1 paper, 2016). A medulloblastoma composed of large cells with prominent nucleoli and a larger amount of cytoplasm in contrast with the cells of the classic medulloblastoma. "Accordingly, our current study reveals that STAT3 nuclear translocation is frequently observed in classical and large-cell medulloblastomas in comparison with the tumor-surrounding brain tissues." (PMID 28035977, 2016). "Statistical correlations were established between p-STAT3 nuclear translocation and the level of SOCS3 (R = 0.333; p = 0.047) or PIAS3 expression (R = −0.494; p = 0.002) but not p-SHP2 down-regulation (R = 0.02; p > 0.05) in the large-cell medulloblastomas." (PMID 28035977, 2016).
Laryngopharyngeal Reflux (1 paper, 2022). Back flow of gastric contents to the LARYNGOPHARYNX where it comes in contact with tissues of the upper aerodigestive tract. "Our data from the use of the three pharmacological inhibitors of STAT3 strongly support their use as promising drugs for the prevention or treatment of inflammatory or neoplastic diseases associated with laryngopharyngeal reflux." (PMID 34850540, 2022).
Lassa fever (1 paper, 2024). A viral hemorrhagic fever that is caused by the Lassa virus, which is transmitted by contact with infected rodents; it is characterized by fever, headache, malaise, myalgia, and hearing loss. "The IFNα and γ response, E2F target, IL6/JAK/STAT3, G2/M checkpoint, IL2/STAT5 and complement pathways were activated during Lassa fever, as shown by comparison with mock-infected animals, but this activation was more intense after Josiah LASV infection." (PMID 39652618, 2024).
Left ventricular dilatation (1 paper, 2021). Enlargement of the chamber of the left heart ventricle. "Other studies have shown that gp130 knockout mice have higher expression of IL-6 binding coreceptors, IL-6, and STAT3 and significantly higher left ventricular dilatations, ruptures, and mortality than control mice." (PMID 33428604, 2021).
leukopenia (1 paper, 2024). "Notably, AKT1, EGFR, IL6, STAT3, BCL2, CASP3, and JUN were identified as the top seven targets (degree >80) and may be key targets of QJSB in treating leukopenia." (PMID 39295929, 2024).
leukoplakia (1 paper, 2015). A white patch or plaque on a mucous membrane that cannot be characterized clinically or pathologically as any other disease. "This theory is supported by HNSCC studies that have demonstrated increased STAT3 activation in normal mucosa from patients with HNSCC as well as in pre-malignant lesions such as leukoplakia." (PMID 26272737, 2015).
listeriosis (1 paper, 2013). A bacterial infection caused by Listeria monocytogenes. "Overall, α-IL6, STAT3 siRNA, and warfarin treatment further illustrated that CYLD impaired IL-6/STAT3-induced fibrin production resulting in impaired pathogen control and death from severe listeriosis." (PMID 23825949, 2013). "In addition, CYLD reduced K63-ubiquitination and phosphorylation of STAT3 resulting in an impaired IL-6/STAT3-dependent production of fibrin by hepatocytes as well as fibrin deposition in the liver, which are also important for protection in listeriosis." (PMID 23825949, 2013). "In listeriosis, IL-6 production and STAT3 activation are initiated within the first hours p.i.." (PMID 23825949, 2013). "In vivo, CYLD also reduced hepatic STAT3 K63-ubiquitination and activation, NF-κB activation, IL-6 and NOX2 mRNA production as well as fibrin production in murine listeriosis." (PMID 23825949, 2013).
Loeys-Dietz syndrome (1 paper, 2021). Loeys-Dietz syndrome is a rare genetic connective tissue disorder characterized by a broad spectrum of craniofacial, vascular and skeletal manifestations with four genetic subtypes described forming a clinical continuum. "The interaction of STAT3 and TGF-β appears important given overlapping phenotypes of STAT3-HIES and Loeys-Dietz syndrome caused by TGFBR1/2 mutations, which manifest with connective tissue disease, raised IgE but an intact Th17 axis." (PMID 33932191, 2021).
lower respiratory tract infection (1 paper, 2022). "Luteolin helped treat acute lower respiratory tract infection by activating STAT1 and alleviating inflammation through both inhibiting STAT3 and activating STAT6." (PMID 36324680, 2022).
lung adenoma (1 paper, 2022). A benign, well circumscribed epithelial neoplasm that arises from the bronchus or the lung parenchyma. "In lung adenoma cells, Mito-HNK treatment decreased the expression of genes associated with complex I, OXPHOS, glycolysis, and STAT3 signaling, while it increased the expression of genes associated with apoptosis and cell death pathways." (PMID 35626143, 2022). "For example, in lung adenoma cells, Mito-HNK treatment inhibited mitochondrial complex I, OXPHOS, and glycolysis, and suppressed the STAT3 pathway." (PMID 35626143, 2022).
lung tumour (1 paper, 2017). "It has been reported that serum IL-6 levels in NSCLC patients (especially metastatic cases) are higher than healthy subjects, and blockade of IL-6/STAT3 signalling results in the inhibition of lung tumour growth." (PMID 29062084, 2017).
macrocytic anemia (1 paper, 2020). Anemia that is characterized by increased red blood cell volume. "Since STAT3 mutation status has been associated with cytopenias, we aimed to evaluate whether macrocytic anemia could be related to STAT3 mutation status." (PMID 32710512, 2020).
macrophage-activated syndrome (1 paper, 2021). "Multiple assumptions for the pathophysiology of this disease have been made including cytokine storm, macrophage-activated syndrome (MAS) limited to the lung, type 1 and 2 interferon signals, IL-6—STAT3 axis, and neutrophil extracellular traps(NETs)." (PMID 32865700, 2021).
macular degeneration (1 paper, 2024). Loss of vision in the central portion of the retina (macula), secondary to retinal degeneration. "R9-SOCS3-KIR was particularly effective against the pathways acting through STAT3, e.g. IL-6 and VEGF-A mediated responses that lead to macular degeneration." (PMID 39104531, 2024).
male reproductive system diseases (1 paper, 2023). "Thus, the JAK2/STAT3 and Keap1/Nrf2 pathways and their components can be considered therapeutic targets for drug design to manage male reproductive system diseases." (PMID 37759514, 2023).
malignant peripheral nerve sheath tumor (1 paper, 2020). Malignant peripheral nerve sheath tumor (MPNST) is a rare and often aggressive soft tissue sarcoma occurring in a wide range of anatomical sites. "In malignant peripheral nerve sheath tumors (MPNSTs), inhibition of STAT3 led to decreased wound healing, cell migration, invasion and tumor formation, while STAT3 knockdown inhibited HIF1-α, HIF2-α and VEGF-A expression." (PMID 32488850, 2020).
minimal change disease (1 paper, 2017).
mucoepidermoid carcinoma (1 paper, 2015). A carcinoma morphologically characterized the presence of cuboidal mucous cells, goblet-like mucous cells, squamoid cells, cystic changes, and a fibrotic stromal formation. "We observed a potent induction of STAT3 phosphorylation upon exposure of mucoepidermoid carcinoma cells (UM-HMC-3A,-3B) to endothelial-conditioned medium, which was partially blocked in a dose-dependent manner with increasing concentrations of tocilizumab." (PMID 26287605, 2015). "Tocilizumab has a significant anti-tumor effect in xenograft mucoepidermoid carcinomas that correlated with potent inhibition of STAT3 signaling and inhibition of tumor angiogenesis." (PMID 26287605, 2015). "Considering the prominent role of STAT3 signalling in the biology of cancer cells, these results provide further support to the therapeutic potential of IL-6R inhibition with tocilizumab in mucoepidermoid carcinoma." (PMID 26287605, 2015). "Here, we used endothelial cell conditioned medium as a physiological strategy to induce activation of major signaling pathways (i.e. STAT3, Akt, ERK) in mucoepidermoid carcinoma cells, to enable the study of potential effects of tocilizumab in these pathways." (PMID 26287605, 2015).
mucormycosis (1 paper, 2015). "While IFN-γ/STAT1 signaling was similar between groups, naïve T cells from patients with IA, but not those with mucormycosis, exhibited reduced responsiveness to IL-6 as measured by STAT3 phosphorylation." (PMID 25835547, 2015).